NRAS (NRAS proto-oncogene, GTPase)
Diseases named in the same sentence as NRAS in open-access papers (continued):
Sharing a sentence is not in itself a finding about the gene and the disease.
melanoma (continued). "We have not found significant correlation between mutational status (BRAF/NRAS) and OS; however, for BRAF or NRAS mutated melanomas we observed significantly shorter disease-free survival (DFS) when compared with wild-type melanoma patients (p = .04; 5-year DFS, 18 vs 19 vs 31 %, respectively)." (PMID 24866436, 2014). "However, this study adds evidence to the importance of the MAPK and PI3K/mTOR pathway in NRAS mutant cancer and supports that these findings are not limited to NRAS mutant melanoma cells." (PMID 25277205, 2014). "Over 60% of melanomas harbor mutations in the BRAF and NRAS genes." (PMID 24550252, 2014). "Approximately 90% of melanomas harbor a point mutation in BRAF, NRAS or cKIT." (PMID 25516806, 2014). "Whether microRNAs (miRNAs) have a role in BRAF- and NRAS-driven melanoma initiation and progression remains to be determined." (PMID 24550252, 2014). "We hypothesized that different cancer types with activating mutations in the same location of NRAS respond to small molecule inhibitors and their combinations in a way comparable to NRAS mutant melanoma cells." (PMID 25277205, 2014). "Our results suggest that combining clinically approved γ–secretase inhibitors, which block Notch activation, with BRAF inhibitors, which block BRAF-MEK-ERK signaling, might be a more effective treatment of BRAF/NRAS mutant melanomas." (PMID 24550252, 2014). "In the current study we analyzed frequency and type of oncogenic mutations in known oncogenes (BRAF, NRAS, and KIT) involved in melanoma development in large contemporary series of MUP patients with long follow-up, and we correlated these outputs with disease clinical features and outcome." (PMID 24866436, 2014). "In melanoma cells harboring the NRAS mutation, the mutated NRAS protein needs CRAF to activate the MEK/ERK pathway, and the BRAF protein is phosphorylated by ERK on S151 near the RAS binding domain, which results in the inhibition of the NRAS/BRAF interaction." (PMID 25422890, 2014). "It is likely that GDC-0623, which is currently in a phase I clinical trial, might be efficacious in melanomas with mutant NRAS." (PMID 24743024, 2014). "Despite these advances, a treatment strategy targeting NRAS-mutated melanoma has not yet been elucidated." (PMID 25422890, 2014). "We therefore asked whether miR-146a expression is upregulated in melanoma cell lines containing mutant BRAF or NRAS." (PMID 24550252, 2014). "Interestingly, melanomas that are wild type for both BRAF and NRAS have almost five times higher mutational loads than tumors where one of these oncogenes is mutated." (PMID 24743024, 2014). "The pathways downstream of NRAS that could be targeted simultaneously in NRAS-mutant melanoma include, but are not limited to, MEK, PI3K/mTOR, and cell-cycle-related targets." (PMID 24743024, 2014). "The RAC1P29S mutation was less frequent, but not mutually exclusive, in NRAS or BRAF mutated melanomas (6.2% vs 12.5%)." (PMID 25344914, 2014). "They found the translocation in 78.6% of the CCSs but in none of the melanomas, whereas BRAF and NRAS mutations were present in, respectively, 51.6 and 12.9% of the melanomas and not in any of the CCSs." (PMID 25593912, 2014). "The major finding of our study is that in contrast to current belief, neither morphology nor the presence of BRAF or NRAS mutation predicts the chance of malignant transformation of a nevus into a melanoma." (PMID 23861977, 2013). "This NRAS/BRAF signaling pathway has attracted considerable attention as a target for anticancer therapy because of its high frequency of mutations and its important role in melanoma disease." (PMID 24416617, 2013). "We also identified one patient with an EGFR-C326S mutation, a position previously seen mutated in glioblastoma, as well as one patient with a NRAS-Q61K mutation, common in melanoma but never seen in gliomas." (PMID 23441165, 2013). "NRAS mutations were not distributed differently between melanomas, associated nevi and control nevi." (PMID 23861977, 2013).
melanoma (continued). "This would make NRAS an attractive therapeutic target in melanoma and once developed, pending an acceptable safety profile, chemotherapy agents that target NRAS could potentially make an important contribution to the future treatment of melanoma." (PMID 27429256, 2013). "Trying to generalize miR-126&126* function, as recipients of miR transduction we selected two metastatic melanoma cell lines characterized by a different mutational status of BRAF and NRAS (i.e. BRAF V600E and NRAS wt for A375M and BRAF wt and NRAS Q61R for Me665/1)." (PMID 23437250, 2013). "In addition, RAS mutations (HRAS, KRAS, or NRAS) have been identified in ∼55–60% of thyroid cancers, and BRAF mutations have been identified in ∼60% of malignant melanomas." (PMID 23991070, 2013). "In sum we show that the presence of a BRAF- or NRAS mutation, at least in the present series, is not biologically relevant in the development of melanomas that arise in association with a nevus." (PMID 23861977, 2013). "NRAS mutant melanoma is mutually exclusive of BRAF mutant melanoma." (PMID 24216705, 2013). "BRAF or NRAS mutated nevi did not have a higher chance to be associated with melanomas than wild type nevi." (PMID 23861977, 2013). "Our results do not support the concept that oncogenic BRAF or NRAS mutations play a major role in the development of melanoma from nevi and do not support the multistep theory of melanoma progression in its current form." (PMID 23861977, 2013). "Due to the overall positive response to treatment reported in this study, a phase II clinical trial (NCT01320085) investigating the safety and efficacy of MEK162 in patients with advanced or unresectable metastatic malignant melanoma, harboring BRAFV600 or NRAS mutations, is currently underway." (PMID 23515890, 2013). "Summary of BRAF, NRAS, and GNAQ mutational status in melanoma cell lines." (PMID 23904987, 2013). "We observed that there was no apparent correlation between dinaciclib response and BRAF/NRAS mutational status, leading us to conclude that dinaciclib had broad-spectrum anti-melanoma activity and was not conclusively mutation specific." (PMID 23527225, 2013). "Other studies also reported that NRAS mutations were detected in ∼10–25% of melanomas and KRAS mutations were detected in ∼30% non-small cell lung cancers (NSCLCs)." (PMID 23991070, 2013). "Some but not all of these cell lines exhibited NRAS mutations, suggesting that some melanomas that are wildtype for both BRAF and NRAS may respond to trametinib, a MEK inhibitor." (PMID 23658559, 2013). "Perhaps, the methodologies used in this preclinical study of NRAS mutant melanoma may be used to evalute a strategy of vicarious RAS targeting to treat sarcomas with elevated Foxm1." (PMID 24216705, 2013). "In fact, it is not completely elucidated how BRAF or NRAS mutations contribute to the emergence of benign melanocytic nevi as they are also the most frequent mutated genes in melanoma, occurring in early stages of tumor progression." (PMID 24222856, 2013). "Elevated RAS/RAF signalling due to oncogenic mutations in BRAF or NRAS is well studied in melanoma, but these mutations are also common in non-proliferating senescent nevi." (PMID 23666755, 2013). "Two BRAF-mutant melanoma patients responded and one NRAS- mutant melanoma patient responded." (PMID 23085539, 2012). "Furthermore, higher doses of inhibitor were required to limit tumour progression in BRAF wildtype and also NRAS mutant melanoma xenografts." (PMID 23039341, 2012). "BRAF and NRAS mutations are absent in melanomas arising in the uveal layer of the eye, but mutually exclusive somatic mutations in the heterotrimeric G protein alpha-subunit, GNAQ, or in GNA11, are present in the great majority of uveal melanomas." (PMID 22515704, 2012).
melanoma (continued). "We report here development, validation, and implementation of an assay designed to simultaneously detect 43 common somatic point mutations in 6 genes (BRAF, NRAS, KIT, GNAQ, GNA11, and CTNNB1) potentially relevant to existing and emerging targeted therapies specifically in melanoma." (PMID 22536370, 2012). "The aim of the current study was to utilize a diverse melanoma cell line panel (n = 31) of known mutational status (BRAF, HRAS, NRAS, and phosphatase and tensin homolog (PTEN)) to aid in the identification of a patient population most likely to respond to MEK inhibition." (PMID 23039341, 2012). "Because of the extensive clinical, histologic, and immunohistochemical similarities with melanoma, we decided to analyze whether CCS also has mutations in the BRAF and NRAS gene." (PMID 22693489, 2012). "Loss of PTEN and RAS activation seems comparable in their ability to increase oncogenic signalling through PI3K pathway, due to the coexistence of PTEN somatic mutations in melanoma harbouring BRAF mutations but not with NRAS." (PMID 22408430, 2012). "At least 6 genes have been shown to be recurrently mutated in melanoma, including the serine-threonine kinase encoded by BRAF; the receptor tyrosine kinase encoded by KIT; the GTP-binding proteins encoded by NRAS, GNA11, and GNAQ; and the WNT signaling pathway component encoded by CTNNB1." (PMID 22536370, 2012). "The absence of BRAF and NRAS mutations in melanoma cell lines is associated with a greater sensitivity to dasatinib in vitro." (PMID 22127285, 2012). "Preclinical studies suggest that some NRAS-mutant cutaneous melanomas may also exhibit sensitivity to RAF or MEK inhibition, whereas KRAS mutations have conferred only marginal sensitivity." (PMID 22515704, 2012). "Overall, the alterations in major components of the MAPK, such as BRAF and NRAS mutations, and mTOR pathways, PTEN loss and AKT overexpression, seem to have substantial influence in melanoma progression, being both pathways linked to survival and chemoresistence in melanoma." (PMID 22408430, 2012). "Despite the fact that the BRAFV600 mutation was the single most prevalent mutation in our melanoma population (51% of the melanomas had a BRAFV600 mutation), 41% of the melanoma tumors contained a PI3K mutation including 10 samples that were wild-type for BRAFV600 and NRAS." (PMID 22912864, 2012). "Among the first 150 melanomas genotyped with informed consent (from 07/08/2010 to 12/13/2010), 90 (60%) had at least one mutation, including 57, 23, 6, 3, and 2 mutations in BRAF, NRAS, GNAQ, KIT, and CTTNB1, respectively." (PMID 22536370, 2012). "Recent studies in melanoma have indicated that some components of the PI3K pathway (PTEN, MTOR, IRS4, PIK3R1, PIK3R4, PIK3R5 and NFKB1) are co-mutated in 17% of BRAF V600E mutant and 9% of NRAS mutant melanomas." (PMID 23006971, 2012). "Specifically NRAS and BRAF mutations are highly associated with melanoma." (PMID 22216021, 2012). "Interestingly, in early clinical trials with MEK inhibitors in unselected patient populations, responses to single agent MEK inhibitor were observed in patients with NRAS mutant melanomas, including one complete response." (PMID 21505228, 2011). "BCL-2 is overexpressed in melanoma: Factors including NRas and MITF may also contribute to increased Bcl-2 activity." (PMID 21479172, 2011). "In addition, PLX4720 enhances the levels of the antiapoptotic BCL-2 family member protein MCL-1 in NRAS mutant melanoma cells through enhanced signaling through the MAPK pathway." (PMID 22175026, 2011). "It is believed that BRAF and NRAS mutations can coexist within the same melanoma but not at the single-cell level." (PMID 22039425, 2011). "Interestingly, as the melanoma DNA yield decreased, there was little drop-off in the percentage of BRAF or NRAS mutations detected using either ARMS or sequencing." (PMID 20925915, 2010).
melanoma (continued). "Furthermore, PLX4032 increased the rate of proliferation of growth factor-dependent NRAS Q61L mutant primary melanoma cells, reduced cell adherence and increased mobility of cells from advanced lesions." (PMID 20149136, 2010). "The results demonstrated that drug response can be modulated by the BRAF genotype but is not affected by mutations in NRAS or downregulation of PTEN in BRAFWT melanoma cells isolated from advanced lesions." (PMID 20149136, 2010). "In addition to inducing BRAF binding to CRAF in NRAS mutant cells, 885-A and sorafenib also induce this binding in WM1791c melanoma cells and in SW620 and HCT116 colorectal carcinoma cells, all of which express mutant KRAS." (PMID 20141835, 2010). "Analysis of BRAF and NRAS mutations in our human melanoma cell lines shows that WM3211 cells do not have the common activating mutations in these genes, yet these cells express increased amounts of HIF-1α protein and mRNA under normoxic conditions." (PMID 19919690, 2009). "We extended these studies to the NRAS mutant melanoma IPC298 cells." (PMID 19492075, 2009). "We found that mutually exclusive mutations of NRAS and BRAF genes occur at quite same rate in cultured and uncultured melanomas (either primary or metastatic lesions), confirming that they represent an early event within the cascade of alterations involved into the melanomagenesis." (PMID 19799798, 2009). "Melanomas also harbor mutations that promote the malignant phenotype, such as in BRAF, CDKN2A, PTEN, CTNNB1, NRAS, PIK3CA and KIT, but except for BRAF (∼50%) and common loss of CDKN2A, these mutations exist in a minor portion of melanoma specimens (10% or less)." (PMID 19234609, 2009). "Targeting both the RAS-effector arms, either by combined BRAF and PIK3CA or MEK1+2 and PIK3CA together, effectively delayed the tumor growth confirming the importance of both the PI3K and RAF effector arms in the IPC298 NRAS-mutant melanoma line for tumor growth." (PMID 19492075, 2009). "C-MET is influenced by NRAS mutations, as NRAS-mutated melanomas, for instance, show higher activation of the C-MET pathway and increased sensitivity to C-MET inhibitors compared to BRAF (human gene that encodes a protein called B-Raf) mutated or wild-type melanomas." (PMID 41563267, 2026). "Among the mutations in melanoma, the most frequently observed are the ones with the presence of the BRAF proto‐oncogene serine/threonine‐protein kinase B‐raf (BRAF) or the NRAS proto‐oncogene GTPase (NRAS) activating mutations—accounting for about 50% and 20%–25% of melanomas, respectively." (PMID 41546170, 2026). "Also, regarding this issue, the presence of pre-operative ctDNA, assessed by ddPCR detecting BRAF and NRAS mutations, was detected in 34% of 119 patients with stage III melanoma who underwent CLND, and was significantly associated with tumor burden and worse MSS." (PMID 39859576, 2025). "This suggests that incorporating anti‐angiogenic drug could extend the survival of mucosal melanoma patients with NRAS mutations to levels comparable to those without NRAS mutations." (PMID 39757723, 2025). "Unlike KRAS and BRAF mutations, NRAS mutations may be more significant in melanoma than CRC, but can still be seen in both cancers." (PMID 40447784, 2025). "BRAF mutation is more frequently found in superficial spreading melanoma/low-cumulative sun damage (Low-CSD) melanomas arising on non-chronic sun-damaged skin; differently, NRAS mutation is more frequent in nodular type and melanoma arising on chronic sun-damaged skin." (PMID 40867317, 2025). "In addition, CRAF primarily activates ERK1/2 in NRAS-mutant melanoma." (PMID 39935431, 2025). "Notably, two patients with phenotypically heterogeneous tumours harbouring MAP2K1D67N mutations had additional BRAF and NRAS mutations: one with a melanocytoma containing BRAFV600E and NRASQ61R, and another with a melanoma containing BRAFG469R and NRASQ61R mutations." (PMID 40107205, 2025).
melanoma (continued). "Of note, parkin protein is expressed in melanocytes but not in melanoma cells, and its expression decreases upon melanocyte transformation by NRAS mutation; downregulation of parkin in melanocytes stimulates their proliferation, while its re-expression in melanoma leads to cell cycle arrest." (PMID 40721981, 2025). "Therefore, the underlying pathogenic process in melanoma may be directly connected to the effects of key mutations (BRAF and NRAS) on the endosomal–lysosomal system, an idea that until now has been underappreciated." (PMID 41155412, 2025). "The hypothesis behind the lack of co-existence involves the pathogenesis of melanoma where either an NRAS or BRAF mutation occurs during the initial development of melanoma and remains stable throughout the disease course." (PMID 39940799, 2025). "Consequently, we hypothesise that the superior response of NRAS mutant melanoma to ICI and anti‐angiogenic combination treatment may be due to its more pronounced abnormal angiogenesis, making it more susceptible to anti‐angiogenic treatment." (PMID 39757723, 2025). "Finally, we noted an increase in NRAS expression in both resistant melanoma cell lines." (PMID 39175042, 2024). "However, the NRAS mutated melanomas in our cohort did not appear to trend toward occurring at more sun-exposed body parts than elsewhere." (PMID 38183457, 2024). "Additionally, PHA665752, a drug that blocks MET phosphorylation, has shown to be effective in targeting NRAS-mutant cells during in vitro studies, indicating the broader effectiveness of Met inhibitors in treating various melanoma subtypes, not only the common BRAFV600E mutant." (PMID 38732242, 2024). "Hence, new therapy options are needed, particularly for those with NRAS-mutant melanoma." (PMID 38727313, 2024). "Furthermore, many studies are testing various experimental treatments for NRAS + melanoma patents." (PMID 39340537, 2024). "This may be anticipated since –unlike NRAS-mutated melanoma cancer cells– normal cells express lower levels of the lncRNA T-RECS and don’t depend on T-RECS to grow and divide." (PMID 38383439, 2024). "Therefore, future studies could benefit from replacing the currently used melanoma cell line, Mel-Ho, which exhibits a BRAF mutation, with one possessing an NRAS mutation, such as Mel Juso." (PMID 39062529, 2024). "Moreover, genes KDM5D, UTY, and NF1 have demonstrated gender differences in lung cancer, while PPP6C and IGF1R exhibit sex-biased expression in melanoma, and the NRAS gene may play sex-specific roles in acute myelogenous leukemia." (PMID 39541191, 2024). "Regardless of whether melanoma with NRAS mutations has been deemed hopeless to treat, there is no doubt that novel splice variants inject new energy into targeted therapy or therapeutic resistance." (PMID 38462618, 2024). "Similarly, profiling of 46 melanoma samples including melanoma samples, patient-derived cultures and cell lines revealed that a differential putative bivalent chromatin state separated the NRAS and BRAF mutant melanoma subtypes." (PMID 38385532, 2024). "However, although the response rate was 40% in treatment-naïve patients with known BRAF mutations, it was only 10% for the cases with BRAF-WT melanoma and none of seven patients with NRAS-mutated melanoma showed a response." (PMID 38263136, 2024). "Furthermore, we showed that these PHB ligands can induce cell apoptosis via the loss of mitochondrial potential (MMP) and caspase activation in many melanoma cells irrespective of BRAF/NRAS mutation status." (PMID 37508519, 2023). "Therefore, treatment for metastatic NRAS-mutant melanoma is based on ICIs." (PMID 38201531, 2023). "Therefore, it might be worth investigating actin polymerization regulation using pharmacologically available drugs such as cytochalasin in NRAS-mutant melanomas." (PMID 36765834, 2023).